CHST9 (carbohydrate sulfotransferase 9)
Description:
Catalyzes the transfer of sulfate from 3'-phosphoadenylyl sulfate (PAPS) to position 4 of non-reducing N-acetylgalactosamine (GalNAc) residues in both N-glycans and O-glycans. Transfers sulfate to the C-4 hydroxyl of terminal beta-1,4-linked GalNAc in the sequence GalNAc-beta-1,4GlcNAcbeta-R found on N-linked oligosaccharides and to the nonterminal beta-1,4-linked GalNAc in chondroitin and dermatan. Required for biosynthesis of glycoprotein hormones lutropin and thyrotropin, by mediating sulfation of their carbohydrate structures. [Isoform 2]: Active against chondroitin but not against terminal beta-1,4-linked GalNAc.
Synonyms: GalNAc-4-ST2; GalNAc4ST-2; GalNAc4ST2
Tractability: Antibody: UniProt places it where antibodies can reach, with high confidence; UniProt predicts a signal peptide or a membrane-spanning region; its Gene Ontology location is reachable by antibodies, with medium confidence.
Gene: Protein-coding gene on chromosome 18 (26,906,481 to 27,185,344, reverse strand). Ensembl gene ENSG00000154080.
Subcellular location: Golgi apparatus membrane (Isoform 1); Secreted (Isoform 2)
Pathways (Reactome):
Metabolism: CS-GAG biosynthesis
Gene Ontology:
Molecular function: dermatan 4-sulfotransferase activity; chondroitin 4-sulfotransferase activity; sulfotransferase activity
Biological process: sulfur compound metabolic process; chondroitin sulfate proteoglycan biosynthetic process; glycosaminoglycan metabolic process; hormone biosynthetic process; proteoglycan biosynthetic process; carbohydrate biosynthetic process; glycoprotein biosynthetic process
Cellular component: Golgi membrane; membrane; extracellular region; Golgi apparatus
Genetic constraint (gnomAD): Loss-of-function variants: 30 observed, 28.6 expected, observed/expected ratio (o/e) 1.05, 90% interval 0.78 to 1.42. The upper end of that interval is the gene's LOEUF score, 1.42, which puts it in group 5 of 6, group 1 being the genes least tolerant of losing a copy. Missense variants: 419 observed, 434.97 expected, observed/expected ratio (o/e) 0.96, 90% interval 0.89 to 1.04. Synonymous variants: 132 observed, 153.49 expected, observed/expected ratio (o/e) 0.86, 90% interval 0.75 to 0.99.
Homologues: Orthologues: chimpanzee CHST9 (99% identical), macaque CHST9 (97% identical), rabbit CHST9 (88% identical), dog CHST9 (88% identical), pig CHST9 (83% identical), guinea pig CHST9 (82% identical), mouse Chst9 (72% identical), rat Chst9 (72% identical). Paralogues in human: CHST8 (46% identical), CHST11 (26% identical), CHST12 (26% identical), CHST10 (24% identical), CHST14 (24% identical), CHST13 (23% identical).
Diseases named in the same sentence as CHST9 in open-access papers:
CHST9 is named in the same sentence as 22 diseases in open-access papers, as found by Europe PMC text mining. Sharing a sentence is not in itself a finding about the gene and the disease. The quoted sentences say what the papers report.
breast carcinoma (3 papers, 2017 to 2020). "Two 18q11.2 genetic variants (CHST9 rs1436904 and AQP4 rs527616) were identified as novel breast cancer susceptibility components based on GWAS24." (PMID 28924212, 2017). "Based on a breast cancer GWAS, which identified AQP4 rs527616 and CHST9 rs1436904 genetic variants, we explored their involvement in early-stage TNBC and concluded that the CHST9 rs1436904 SNP is an independent prognostic genetic variant in Chinese TNBC patients." (PMID 28924212, 2017). "Nevertheless, the role of CHST9 as well as its genetic variations in breast cancer, especially TNBC, has not been determined." (PMID 28924212, 2017).
schizophrenia (3 papers, 2015 to 2019). A major psychotic disorder characterized by abnormalities in the perception or expression of reality. "Among them, a variant at CHST9 was first selected to further investigate due to its previously reported association with schizophrenia via CNVs5." (PMID 31481703, 2019). "Statistical analyses from both the case-control and family-based analyses indicated that the CA deletion from CHST9 gene was significantly associated with schizophrenia in the Chinese population." (PMID 31481703, 2019). "In this study, the CA deletion of CHST9 gene is significantly associated with the diagnosis of schizophrenia." (PMID 31481703, 2019). "Overall, in either the case-control or segregation analyses, we found that the CA deletion in CHST9 gene from our family study was associated with schizophrenia in the Chinese population." (PMID 31481703, 2019). "In that report, a CNV of CHST9 was found to be associated with schizophrenia." (PMID 31481703, 2019). "It is possible that the loss of function of the CHST9 protein may interfere with normal brain development, and thus contribute to the development of schizophrenia." (PMID 31481703, 2019). "We found a two-base-pair CA deletion in the CHST9 gene in three schizophrenia cases from two independent families." (PMID 31481703, 2019). "In the candidate CNV regions, 26 regions had no overlaps with the common CNVs found in Asian populations and included the genes (i.e., ANTXRL, CHST9, DNM3, NDST3, SDK1, STRC, SKY) that are associated with schizophrenia and/or other psychiatric diseases." (PMID 26136833, 2015). "Additionally, CHST9 CNV and amplification are also found in the brain of schizophrenia patients and gastric cancer patients with metastatic lymph node." (PMID 28924212, 2017).
triple-negative breast carcinoma (3 papers, 2017 to 2025). An invasive breast carcinoma which is negative for expression of estrogen receptor (ER), progesterone receptor (PR), and human epidermal growth factor receptor 2 (HER2). "Genetic variants of CHST9 contribute to the prognosis of triple-negative breast cancer and the copy number variants of CHST9 are associated with hematologic malignancies." (PMID 35456975, 2022).
gastric cancer (2 papers, 2015 to 2017). A primary or metastatic malignant neoplasm involving the stomach. "Gastric cancer sometimes metastasizes to lung, and therefore it would be interesting to determine if CHST9 plays a causative role in the formation of such GAGs in the lung metastasis of gastric cancer." (PMID 25154973, 2015).
autism (1 paper, 2015). Persistent deficits in social interaction and communication and interaction as well as a markedly restricted repertoire of activity and interest as well as repetitive patterns of behavior. "ANTXRL and CHST9 are located in the CNV regions associated with bipolar disorder and autism." (PMID 26136833, 2015).
dementia (1 paper, 2025). Loss of intellectual abilities interfering with an individual's social and occupational functions. "Notably, several CHST9 variants were also associated with HFRS without dementia and similarly exhibited colocalization with eQTL." (PMID 40764432, 2025).
glioma (1 paper, 2022). A benign or malignant brain and spinal cord tumor that arises from glial cells (astrocytes, oligodendrocytes, ependymal cells). "No published evidence was available as to the roles of the remaining eight underexpressed gene signatures (CHST9, CSDC2, ENHO, FERMT1, IGFN1, LINC00836, MGAT4C and SHANK2) regarding glioma pathogenesis or prognosis." (PMID 35456975, 2022).
liver disease (1 paper, 2022). "Finally, several genes in the [NASH]vs[NAFLD + HC] signature (e.g. CHST9, DPYSL2) have not been previously implicated in liver disease and could potentially provide novel biological insights into NASH etiology." (PMID 35173224, 2022).
lymph-node metastasis (1 paper, 2017). "Stratified analyses showed an increased risk of cancer progression in CHST9 rs1436904G allele carriers harboring larger tumor (tumor size > 2 cm), without lymph-node metastasis, being premenopausal at diagnosis or with vascular invasion (P = 0.032, 0.017, 0.008 or 0.003)." (PMID 28924212, 2017). "Among the TNBC patients without lymph-node metastasis, the mean DFS of the CHST9 rs1436904 GG genotype was significantly shorter than that of the TT genotype patients (48.1 months vs. 62.6 months; P = 0.033)." (PMID 28924212, 2017). "We found that the CHST9 rs1436904 polymorphism might be a potential prognostic biomarker for early-stage TNBC, especially in the patients harboring larger tumor (tumor size > 2 cm), without lymph-node metastasis, being premenopausal at diagnosis or with vascular invasion." (PMID 28924212, 2017).
tumor (5 papers, 2013 to 2025). "In the subgroup of TNBC patients harboring large tumors (tumor size > 2 cm), the CHST9 rs1436904 G allele (GT and GG genotype) was associated with a significantly increased risk of disease progression (HR = 1.88, 95% CI = 1.06–3.35; P = 0.032) compared to the TT genotype." (PMID 28924212, 2017). "All seven prognostic characteristics were prominently expressed in TCGA‐LIHC, with the exception of CHST9, which exhibited significantly lower expression levels in the tumour group." (PMID 39428564, 2024). "Moreover, in both the TCGA‐LIHC and ICGC‐LIRI‐JP datasets, the expression of other prognostic features was elevated in tumour tissues, with the exception of CHST9." (PMID 39428564, 2024). "Additionally, RT‐qPCR analysis indicated that CHST9 was expressed at low levels in tumour samples, while HMGN4, ITGAV, RAP2A, TMCO3, and ZFYVE26 displayed high expression levels." (PMID 39428564, 2024). "Interestingly, the CHST9 gene also harbor potential oncogenic features, as it is commonly amplified in various neoplasia." (PMID 34944959, 2021). "Moreover, the mutations ALPK2.R136S, CHST9.S122N, FAM38B.V2463, LAMA1.S1577A, LAMA1.K2002E, MYOM1.T215M, SERPINB10.R246C and SLC14A2.A880T were found in all three tumor samples and shared a similar frequency profile." (PMID 23892400, 2013).
CHST9 also shares sentences with these, for which no sentence is quoted: cancer (5 papers); hematologic malignancies (4); acute myelogenous leukemia (2); psychiatric diseases (2); bipolar disorder (1); colon cancer (1); hepatocellular carcinoma (1); lung carcinoma (1); membranous nephropathy (1); ovarian carcinoma (1); thyroid tumor (1); uterine corpus endometrial carcinoma (1).